SIRT1 (sirtuin 1)
Diseases named in the same sentence as SIRT1 in open-access papers (continued):
Sharing a sentence is not in itself a finding about the gene and the disease.
hepatocellular carcinoma (155 papers, 2011 to 2026). A malignant tumor that arises from hepatocytes. "Bioinformatics analysis has revealed a significant association between SIRT1 and ferroptosis in both hepatocellular carcinoma (HCC), gastric cancer and Ewing’s sarcoma, highlighting its potential as a therapeutic target in these diseases." (PMID 40109363, 2025). "As for the liver, only one study indicated that the overexpression of miR-204-5p in human hepatocellular carcinoma cell lines targeted SIRT1 and caused the suppression of cell survival and the increase of apoptosis and drug sensitivity." (PMID 35299765, 2022). "To investigate the mechanism(s) underlying the reduction in CEACAM1, we overexpressed SIRT1 in HepG2 human hepatoma cells via adenoviral-mediated delivery." (PMID 34948019, 2021). "SIRT1 elevation has been associated with tumor progression and a worse prognosis in several cancer types (e.g., bladder, breast, hepatocellular carcinoma, gastric, and pancreatic cancer)." (PMID 30445998, 2018). "SIRT1 was first linked with hypoxia inducible factor (HIF) activity in hepatoma cells, where HIF-2 was acetylated at its C-terminal and consequential decrease in its transcriptional activity." (PMID 28197299, 2017). "Another nine included studies analyzed the associations between SIRT1 expression and OS in hepatocellular carcinoma, pancreatic cancer, gastric cancer, esophageal squamous cell carcinoma, and gastroesophageal junction cancer." (PMID 28977971, 2017). "Nevertheless, evidence from different laboratories has suggested that SIRT1 expression is elevated and associated with tumor growth in prostate tumor and hepatocellular carcinoma respectively." (PMID 24416313, 2014). "Studies confirm its regulatory influence over hepatocellular carcinoma progression through SIRT1 modulation and its intimate link with hepatoblastoma via angiogenic control mediated by the JAK2/STAT3 pathway." (PMID 41523988, 2026). "SIRT1 plays a dual role in hepatocellular carcinoma (HCC), acting both as a tumor promoter and a tumor suppressor, depending on the context." (PMID 40052151, 2025). "Next, we treated human hepatoma Huh7 cells with recombinant human Sirtuin-1 (rhSIRT1) protein to mimic the circulating SIRT1 protein." (PMID 40653676, 2025). "HepG2, PLC/PRF/5, and MHCC97H hepatocellular carcinoma cells were transiently transfected with SIRT1-overexpressing plasmids, treated with 1.25 μM 1-P for 4 h, exposed to 625 nm light irradiation (1 h), and further incubated for 20 h." (PMID 40872615, 2025). "Among malignancies, hepatocellular carcinoma (HCC) represents the most comprehensively studied context for SIRT1." (PMID 41208649, 2025). "The pharmacological inhibition or gene knockdown of SIRT1 upregulated VLDLR protein levels in the human Huh-7 hepatoma cell line, with this increase abolished by the pharmacological inhibition of HIF-1α." (PMID 38807218, 2024). "For example, diallyl trisulfide induces pro-death autophagy in hepatocellular carcinoma through the AMPK/SIRT1 axis." (PMID 39403142, 2024). "SIRT1 plays a critical role in promoting autophagy and modulating NF-κB signaling in both sorafenib-resistant and parental hepatocellular carcinoma cells, highlighting its potential as a therapeutic target in HCC treatment." (PMID 39315094, 2024). "In human hepatoma cells, serum from calorie‐restricted volunteers increased longevity markers such as Sirtuin 1 and PGC‐1α, and enhanced stress resistance." (PMID 37060190, 2023). "SIRT1 expression is drastically reduced in various cancers, including hepatic carcinoma, and its activation inhibits cancer growth." (PMID 37715252, 2023). "Studies have also demonstrated that miR-204 down-regulates the expression of Bcl-2, Sirt1, and Fn-1 to inhibit the proliferation and promote the apoptosis of hepatoma cells and tumor endothelial cells." (PMID 37488484, 2023).
hepatocellular carcinoma (continued). "USP22 can promote multidrug resistance (MDR) in hepatocellular carcinoma cells by activating the SIRT1/AKT/MRP1 pathway, which contributes to tumorigenesis and progression of hepatocellular carcinoma." (PMID 36176401, 2022). "This study further analysed the stem cell-like properties and mechanism of GNL3 through SIRT1 in hepatocellular carcinoma cells." (PMID 35432540, 2022). "Resveratrol also inhibited proliferation and migration through sirtuin 1-mediated post-translational modification of the PI3K/Akt pathway in hepatocellular carcinoma cells." (PMID 36500361, 2022). "First, we overexpressed constitutively active or dominant negative forms of SIRT1 in HepG2 human hepatoma cells." (PMID 35419389, 2022). "The expression level of SIRT1 was also detected in human hepatoma Huh-7 cells transiently transfected with HBV expressing plasmid pCH9/3091 (containing a 1.1-unit length HBV genome driven by a cytomegalovirus promoter)." (PMID 32714081, 2020). "Through the help of RNA interference, they checked the overexpression and selective silencing of SIRT1 in hepatoma and normal cell lines and found a significantly higher overexpression of SIRT1 in hepatoma cell lines compared with normal cell lines." (PMID 32607257, 2020). "It has been reported that RSV treatment attenuates protein oxidation and improves SOD, GPx, CAT, GST, and GSH levels through the activation of Nrf2 mRNA levels and SIRT1 in diabetic rats and human liver carcinoma cells." (PMID 30987086, 2019). "We then demonstrated that overexpression of miR-124 sensitized cisplatin-induced cytotoxicity against CD133+ hepatocellular carcinoma cells by targeting SIRT1/ROS/JNK pathway." (PMID 31056532, 2019). "As SIRT1 has been reported to act as a potential oncogene, it is usually overexpressed in multiple human cancers including hepatocellular carcinoma, osteosarcoma, lung cancer and colorectal cancer." (PMID 31056532, 2019). "However, the overexpression of SIRT1 is linked with hepatocellular carcinoma cells (HCC) and tumor tissues, where it helped migration and invasion of HCC along with tumor metastasis in vivo by inducing epithelial-mesenchymal transition." (PMID 31354914, 2019). "have found reduced SIRT1 expression in several types of cancer (glioblastoma, bladder carcinoma, prostate carcinoma, ovarian cancer, and hepatic carcinoma), compared to the corresponding normal tissues." (PMID 31747893, 2019). "The long non-coding RNA (lncRNA) metastasis associated lung adenocarcinoma transcript 1 (MALAT1) was recently discovered to interfere with SIRT1 activity in hepatocellular cancer." (PMID 30319549, 2018). "The importance of SIRT1 in hepatic autophagy regulation has been reported in ischemic livers, hepatocellular cancer, and hepatosteatosis." (PMID 29774638, 2018). "In hepatocellular carcinoma, SIRT1 promotes accumulation of HIF-α and activates transcription of HIF-1alpha target genes." (PMID 28197299, 2017). "Luciferase assays also showed that SIRT1 suppresses PPARγ2-induced MGAT1 promoter activity in human hepatoma-derived HepG2 cells." (PMID 27404390, 2016). "Western blot analysis showed that MCL1 was overexpressed in two human hepatocellular carcinoma cell lines, while SIRT1 was elevated in all the examined cell lines." (PMID 25888625, 2015). "This will provide novel insights concerning the potential of NAMPT and SIRT1 as therapeutic targets in hepatocellular carcinoma." (PMID 24603648, 2014). "It was shown that AMPK can directly phosphorylate SIRT1 on T344, thereby inhibiting SIRT1 activity in human hepatocellular carcinoma cells." (PMID 25070626, 2014).
hepatocellular carcinoma (continued). "Multiple studies have demonstrated a positive correlation between MYC and SIRT1 expression in various human cancers, including hepatocellular carcinoma and colorectal cancer." (PMID 25085992, 2014). "We have recently found that SIRT1 expression is highly elevated in hepatocellular carcinoma, and the depletion of SIRT1 leads to substantial reduction in TERT mRNA and protein expression." (PMID 24416313, 2014). "This study investigated SIRT1 expression and its prognostic value in hepatocellular carcinoma (HCC)." (PMID 25522783, 2014). "In particular, SIRT1 expression and activity are increased in human hepatoma and fibrosarcoma cells in vitro." (PMID 23442768, 2013). "Observations that link high Sirt1 expression to poorly differentiated cancers were also made by other investigators for hepatocellular carcinoma, prostate cancer and glioblastoma." (PMID 24088390, 2013). "While several studies found deregulation of Sirt1 in various tumor entitites including ovary, prostate, gastric, colon, hepatocellular carcinoma as well as melanoma and glioblastoma, comprehensive in vivo data in pancreatic cancer is still missing." (PMID 24088390, 2013). "We sought to elucidate the role of SIRT1 in liver cancer under the influence of c-Myc and to determine the prognostic significance of SIRT1 and c-Myc expression in human hepatocellular carcinoma." (PMID 23024800, 2012). "The prognostic significance of the immunohistochemical detection of SIRT1 and c-Myc was evaluated in 154 hepatocellular carcinoma patients." (PMID 23024800, 2012). "In hepatocellular carcinoma, miR-486-5p diminishes Sirt1 expression by binding to its 3′UTR, thereby inhibiting the expression of stem cell-related genes (e.g., SOX2, OCT4, and CD13) and ultimately suppressing the self-renewal capacity of hepatocellular carcinoma cancer stem cells (CSCs)." (PMID 40710326, 2025). "For example, in cancers such as hepatocellular carcinoma, pancreatic cancer, and some forms of leukemia, SIRT1 is often upregulated, which leads to enhanced survival of cancer cells through the suppression of apoptosis and the activation of pro-survival pathways." (PMID 39403142, 2024). "This suggests that the overexpression of H2AZ1 in hepatocellular carcinoma may indirectly regulate oxidative stress by targeting TFs such as SIRT1 and YY1." (PMID 38305811, 2024). "Actually, Lira has already been demonstrated to ameliorate pyroptosis in cardiomyoblast cell lines (H9c2) and hepatocellular carcinoma (HepG2) cell lines through increasing SIRT1 expression level, reducing intracellular reactive oxygen species, and promoting mitophagy." (PMID 34985189, 2022). "In addition, USP22 can directly interact with SIRT1 and regulate the protein expression level of SIRT1, which promotes the resistance of hepatoma cells to 5-fluorouracil (5-FU)." (PMID 35875077, 2022). "Thus, HULC can not only increase the expression of P62 by reducing mature miR-15a, but also increase autophagy by increasing Sirt1-dependent LC3II to promote the development of hepatocellular carcinoma." (PMID 35183058, 2022). "In the present study, we explored the unique role of GS, which could be a modulator of Sirt1 activities, using two different human liver cell lines, such as the hepatoma cell line and HSCs cell line." (PMID 36670959, 2022). "Previous studies indicated that the expression of SIRT1 was upregulated in hepatocellular carcinoma tissues, and could directly deacetylate p62 to prevent its degradation." (PMID 35252011, 2022). "At the same time, UNC1999 could increase the sensitivity of hepatoma cell lines to sorafenib by down regulating SIRT1, FGF21, FGF21 and VEGFR2." (PMID 34976797, 2021). "Therefore, targeting Sirt1 or p62 is a reasonable strategy for the treatment of hepatocellular carcinoma." (PMID 33854041, 2021).
hepatocellular carcinoma (continued). "Likewise, Sirt1 overexpression plays a crucial anti-apoptotic role, but inhibition of Sirt1 can increase sensitivity towards chemo-drugs in hepatocellular carcinoma or acute myeloid leukemia." (PMID 32570218, 2020). "MNX-AS1 was reported to act as a functional oncogene that induces aggressiveness by numerous manners such as activating MAPK pathway in cervical cancer and acting as a sponge to miR-218-5p/COMMD8 axis in hepatocellular carcinoma and to miR-34a/SIRT1 axis in esophageal squamous cell carcinoma." (PMID 32754442, 2020). "Moreover, hypoxia-induced radioresistance is attenuated by resveratrol in human hepatoma cells (HepG2) through SirT1 activation and c-Myc downregulation, while resveratrol treatment did not alter the radiosensitivity of normoxic hepatoma cells." (PMID 30791624, 2019). "It has been suggested that a significant increase of SIRT1 expression in hepatocellular carcinoma; breast, prostate, ovarian, gastric, and colon cancers; glioblastoma; and lymphoma might be associated with the development and invasion of tumors." (PMID 31781300, 2019). "Moreover, PGC-1α mediates the pro-metastatic functions of SIRT1 in other cancers such as hepatocellular carcinoma, further strengthening the importance of the SIRT1-PGC-1α axis in cancer." (PMID 29629336, 2018). "It was reported that one new dammarane-type triterpenes isolated from stems–leaves of Panax ginseng could activate SIRT1 to inhibit the proliferation of human leukemia HL-60 cells and human hepatocellular carcinoma Hep-G2 cells." (PMID 29991742, 2018). "Next, we asked if SIRT1 level was also sensitive to GA in HepG2 human hepatoma cells and it was." (PMID 30463299, 2018). "In conclusion, our meta-analysis showed that high SIRT1 expression was clearly associated with worse OS in non-colorectal gastrointestinal cancer, in particular in hepatocellular carcinoma and gastric cancer." (PMID 28977971, 2017). "We next investigated the effects of SIRT1 expression on hepatoma cell invasion and metastasis." (PMID 27081083, 2016). "In addition, high SIRT1 expression has been proposed as a poor prognostic factor in breast and liver carcinoma." (PMID 25915617, 2015). "Thus, mice that received a single injection of the hepatocarcinogen, DEN, and were then exposed to a high-fat diet for 11 months had a 100% incidence of hepatic carcinomas, while mice overexpressing SIRT-1 were clearly protected." (PMID 25533006, 2014). "In this review, we provide a comprehensive overview of the roles of SIRT1 in multiple liver diseases, including metabolic dysfunction-associated steatotic liver disease (MASLD), alcohol-associated liver disease (ALD), liver fibrosis, and hepatocellular carcinoma (HCC)." (PMID 41281762, 2025). "EX-527 has shown the highest efficacy in models with upregulated SIRT1 activity, as demonstrated in hepatocellular carcinoma (HCC) cell lines HepG2 and Huh7." (PMID 41425255, 2025). "In hepatocellular carcinoma (HCC), SIRT1 is overexpressed and correlates with tumor grade, predicting adverse clinical outcomes and poor prognosis." (PMID 40149420, 2025).
hepatocellular carcinoma (continued). "A latest study showed that the activation of mitochondrial fission downregulated PGC-1α/PPARα signaling in hepatocellular carcinoma (HCC) cells and inhibited SIRT1 driving metabolic reprogramming in HCC." (PMID 36647167, 2023). "In addition, USP22 may induce autophagy through deubiquitination of SIRT1, thereby reducing the sensitivity of hepatoma cells to chemotherapeutic drugs." (PMID 35935969, 2022). "In addition, a study of hepatocellular carcinoma demonstrated that CDK9 inhibition reduced SIRT1 phosphorylation and SIRT1-mediated deacetylation of FOXO3, and inhibited FOXO3 activity and BNIP3 transcription, thereby blocking the activation of PINK1-PRKN-mediated mitophagy." (PMID 36507335, 2022). "CPEB1 might also target the 3′-UTR of SIRT1 to suppress the growth of hepatic carcinoma." (PMID 33892791, 2021). "Moreover, Sirt1 was up-regulated to deacetylate and stabilize p62 in hepatocellular carcinoma." (PMID 33854041, 2021). "In hepatocellular carcinoma (HCC), SIRT1 was found to inhibit metastasis formation by promoting M1 macrophage polarization." (PMID 32117717, 2020). "Down-regulation of SIRT1 was shown to mediate the reduction in PGC-1α activity and consequent mitochondrial dysfunction in a model of glycogen storage disease 1a deficient in G6Pase-a, a progressive liver disease that can result in hepatocellular adenoma and hepatocellular carcinoma." (PMID 31060333, 2019). "SIRT1 is upregulated in the majority of hepatocellular carcinomas (HCCs) and enhances the invasive and metastatic potential of HCC by activating EMT markers, such as SNAIL, TWIST, and VIMENTIN, and inhibiting E-cadherin." (PMID 30761005, 2019). "In addition, both SIRT1 and c-Myc may be useful prognostic indicators of hepatocellular carcinoma and SIRT1 targeted therapy may be beneficial in the treatment of hepatocellular carcinoma." (PMID 23024800, 2012). "In hepatocellular carcinoma (HCC), RSV (10–100 μM) inhibits PI3K/Akt phosphorylation via SIRT1-mediated deacetylation, with > 50% suppression of p-Akt at 48 h, thereby suppressing cell proliferation and migration." (PMID 40690143, 2025). "In hepatocellular carcinoma (HCC), SIRT1 deacetylates p62 at K295, preventing its degradation, activating mTORC1, and promoting hepatocarcinogenesis, while PCAF enhances autophagic flux by inhibiting Akt/mTOR, thereby inducing cancer cell death." (PMID 41213956, 2025). "Metformin has been explored as an adjuvant therapy for HCC, as low doses promote hepatoma cell senescence by activating the AMPK pathway and inhibiting SIRT1, offering a strategy to reduce tumor growth." (PMID 40052151, 2025). "The SIRT1 and SIRT2 inhibitors, cambinol and EX-527, were utilized in the context of hepatocellular cancer." (PMID 39479446, 2024). "miR-449 can inhibit SIRT1-SREBP signaling by reducing the expression of SIRT1, SREBP1c, and its downstream genes FASN and HMGCR, thereby controlling adipogenesis and cholesterol production in hepatoma cells." (PMID 36969840, 2023). "A previous study indicated that galangin is capable of upregulating Sirt1 and deacetylated LC3, which in turn induces hepatocellular carcinoma autophagy and apoptosis." (PMID 35163314, 2022). "Similarly, RSV activated SIRT1, reduced NFkB, and acted against alcohol-aflatoxin B1-induced Hepatocellular carcinoma (HCC)." (PMID 36558430, 2022). "SIRT1 has been shown to promote OXPHOS and mitochondrial biogenesis in adipocytes and hepatocellular carcinoma cells by regulating the expression of mitochondrial transcription factor A (TFAM)." (PMID 35641987, 2022).